PCDHB2 (protocadherin beta 2)
Description:
Potential calcium-dependent cell-adhesion protein. May be involved in the establishment and maintenance of specific neuronal connections in the brain.
Synonyms: PCDH-BETA2
Tractability: Antibody: its Gene Ontology location is reachable by antibodies, with high confidence; UniProt places it where antibodies can reach, with medium confidence; UniProt predicts a signal peptide or a membrane-spanning region. PROTAC: ubiquitination databases record sites on it.
Gene: Protein-coding gene on chromosome 5 (141,094,606 to 141,098,703, forward strand). Ensembl gene ENSG00000112852.
Subcellular location: Cell membrane
Subcellular location (Human Protein Atlas): Nucleoplasm
Gene Ontology:
Molecular function: cell adhesion molecule binding; calcium ion binding
Biological process: calcium-dependent cell-cell adhesion; cell adhesion; chemical synaptic transmission; nervous system development; synapse assembly; homophilic cell-cell adhesion
Cellular component: membrane; plasma membrane; synapse
Genetic constraint (gnomAD): Loss-of-function variants: 0 observed, 0.0767 expected, observed/expected ratio (o/e) 0, 90% interval 0 to 1.89. That is too few expected variants to judge how well the gene tolerates losing a copy. Missense variants: 914 observed, 1,028 expected, observed/expected ratio (o/e) 0.89, 90% interval 0.84 to 0.94. Synonymous variants: 395 observed, 459.96 expected, observed/expected ratio (o/e) 0.86, 90% interval 0.79 to 0.93.
Homologues: Orthologues: macaque PCDHB2 (96% identical), mouse Pcdhb2 (76% identical), rat Pcdhb2 (76% identical). Paralogues in human: PCDHB3 (80% identical), PCDHB14 (78% identical), PCDHB7 (76% identical), PCDHB16 (75% identical), PCDHB6 (75% identical), PCDHB11 (75% identical), PCDHB15 (74% identical), PCDHB10 (74% identical), PCDHB12 (74% identical), PCDHB5 (74% identical), PCDHB8 (74% identical), PCDHB13 (74% identical), and 49 more.
Diseases named in the same sentence as PCDHB2 in open-access papers:
PCDHB2 is named in the same sentence as 5 diseases in open-access papers, as found by Europe PMC text mining. Sharing a sentence is not in itself a finding about the gene and the disease. The quoted sentences say what the papers report.
retinoblastoma (1 paper, 2025). A malignant tumor that originates in the nuclear layer of the retina. "Moreover, genome-wide methylation profiling of aqueous humor cfDNA has defined robust subtypes of retinoblastoma linked to clinical outcomes, identifying differentially methylated genes (e.g., TFF1, BCHE, PCDHB2, ADAM33) that correlate with aggressive disease and chemoresistance." (PMID 41150792, 2025).
cancer (1 paper, 2022). A tumor composed of atypical neoplastic, often pleomorphic cells that invade other tissues. "We obtained a six-gene signature (APOBEC3B, GOLM1, FAM117A, KCNQ1OT1, PCDHB2, and USP43) with the ability to predict overall survival and progression-free survival (PFS), which could translate into a prediction of the response to the cancer treatment received." (PMID 35565183, 2022).
tumor (1 paper, 2022). "In this study, PCDHB2, PCDHB4, and PCDHB6 were overexpressed in the HCCW4 subgroup, in association with worse survival; this finding contradicts a tumor suppressor role." (PMID 36230503, 2022).
PCDHB2 also shares sentences with these, for which no sentence is quoted: liver cancer (1 paper); ovarian carcinoma (1).